MSTN (myostatin)
Description:
Acts specifically as a negative regulator of skeletal muscle growth.
Synonyms: GDF8; MSLHP
Tractability: Antibody: a drug acting on it is in phase 2 or 3 trials; UniProt places it where antibodies can reach, with medium confidence; UniProt predicts a signal peptide or a membrane-spanning region; its Gene Ontology location is reachable by antibodies, with medium confidence. PROTAC: a small molecule that binds it is known. Other modalities: a drug acting on it is in phase 2 or 3 trials.
Target class: Secreted protein
Gene: Protein-coding gene on chromosome 2 (190,055,700 to 190,062,729, reverse strand). Ensembl gene ENSG00000138379.
Subcellular location: Secreted
Pathways (Reactome):
Gene expression (Transcription): FOXO-mediated transcription of cell cycle genes
Gene Ontology:
Molecular function: cytokine activity; identical protein binding; protein binding; signaling receptor binding; growth factor activity; heparin binding; protein homodimerization activity
Biological process: muscle cell cellular homeostasis; negative regulation of myoblast differentiation; negative regulation of phosphatidylinositol 3-kinase/protein kinase B signal transduction; negative regulation of skeletal muscle tissue growth; positive regulation of DNA-templated transcription; muscle organ development; myoblast migration involved in skeletal muscle regeneration; negative regulation of myoblast proliferation; negative regulation of satellite cell differentiation; negative regulation of skeletal muscle satellite cell proliferation; positive regulation of lamellipodium assembly; positive regulation of macrophage chemotaxis; skeletal muscle tissue development; transforming growth factor beta receptor signaling pathway; trophoblast cell migration; cellular response to hypoxia; negative regulation of insulin receptor signaling pathway; negative regulation of muscle hypertrophy; ovulation cycle process; response to electrical stimulus; response to estrogen; response to ethanol; response to glucocorticoid; response to gravity; response to muscle activity; and 4 more
Cellular component: extracellular region
Genetic constraint (gnomAD): Loss-of-function variants: 12 observed, 34.08 expected, observed/expected ratio (o/e) 0.35, 90% interval 0.22 to 0.57. The upper end of that interval is the gene's LOEUF score, 0.57, which puts it in group 2 of 6, group 1 being the genes least tolerant of losing a copy. Missense variants: 403 observed, 474.32 expected, observed/expected ratio (o/e) 0.85, 90% interval 0.78 to 0.92. Synonymous variants: 168 observed, 164.26 expected, observed/expected ratio (o/e) 1.02, 90% interval 0.9 to 1.16.
Homologues: Orthologues: chimpanzee MSTN (99% identical), macaque MSTN (99% identical), pig MSTN (98% identical), rabbit MSTN (98% identical), guinea pig MSTN (97% identical), mouse Mstn (96% identical), dog MSTN (96% identical), rat Mstn (95% identical), tropical clawed frog mstn (76% identical), tropical clawed frog mstn.2 (70% identical). Paralogues in human: GDF11 (62% identical), TGFB3 (27% identical), BMP6 (26% identical), TGFB2 (25% identical), BMP5 (24% identical), BMP7 (24% identical), TGFB1 (24% identical), BMP10 (24% identical), BMP8A (23% identical), BMP8B (23% identical), INHBB (23% identical), BMP2 (22% identical), and 19 more.
Diseases named in the same sentence as MSTN in open-access papers:
MSTN is named in the same sentence as 273 diseases in open-access papers, as found by Europe PMC text mining. Sharing a sentence is not in itself a finding about the gene and the disease. The quoted sentences say what the papers report.
sarcopenia (305 papers, 2007 to 2026). Progressive decline in muscle mass due to aging which results in decreased functional capacity of muscles. "This study investigated the associations of serum myostatin and irisin levels with sarcopenia and OP prevalence in 182 rheumatoid arthritis (RA) versus 142 healthy controls." (PMID 40593203, 2025). "Sharp scores (OR = 1.008; 95% CI: 1.002–1.014; P = 0.013) and higher serum myostatin levels (OR = 1.222; 95% CI: 1.015–1.472; P = 0.034) were significant risk factors for sarcopenia in RA patients." (PMID 40593203, 2025). "In a translational study, elevated myostatin promoted muscle loss by enhancing protein breakdown and autophagy, linking liver dysfunction to sarcopenia." (PMID 41515940, 2025). "Regression analysis revealed that Sharp scores and elevated myostatin levels were risk factors for sarcopenia in RA patients, whereas irisin served as a protective factor." (PMID 40593203, 2025). "Receiver operating characteristic (ROC) curve analysis yielded an area under the curve (AUC) of 0.69 for myostatin in identifying sarcopenia, with an optimal diagnostic cut-off value of 390 pg/mL." (PMID 41464844, 2025). "In conclusion, targeting myostatin and activin A presents a promising avenue for developing therapies to prevent muscle wasting associated with cachexia and sarcopenia." (PMID 39764565, 2025). "Conversely, elevated GDF8 (myostatin) exacerbates muscle loss and metabolic dysfunction, presenting a therapeutic target for obesity-related sarcopenia." (PMID 40301996, 2025). "By contrast, serum MSTN level was inversely associated with severe sarcopenia [OR: 0.98 (CI: 0.964–0.997), p=0.025]." (PMID 40661742, 2025). "MSTN signaling pathway activation is a potential mechanism suggested for underlying sarcopenia in CKD." (PMID 40243849, 2025). "In logistic regression, ApoJ was independently associated with sarcopenia (OR = 1.027, p = 0.006) and severe sarcopenia (OR = 1.041, p = 0.027), while MSTN was inversely associated with severe sarcopenia (OR = 0.980, p = 0.025)." (PMID 40661742, 2025). "Elevated circulating ApoJ levels were independently associated with an increased risk of sarcopenia, whereas higher MSTN levels were positively correlated with greater muscle strength and better PP in older adults." (PMID 40661742, 2025). "First, due to its cross-sectional design, causality between ApoJ and MSTN levels and sarcopenia cannot be established." (PMID 40661742, 2025). "In older individuals, elevated MSTN protein and mRNA levels are linked to reduced fat-free mass, implying that MSTN plays a role in sarcopenia development." (PMID 41011274, 2025). "Some studies suggest increased myostatin levels with age and indeed myostatin/activin pathway dysregulation is strongly implicated in the development of sarcopenia." (PMID 40678078, 2025). "According to the authors, increased myostatin levels are a risk factor for sarcopenia, while irisin levels serve as a protective factor." (PMID 40862708, 2025). "Reduced irisin levels therefore enhance myostatin-driven muscle loss, whereas higher irisin levels help protect against sarcopenia." (PMID 41515940, 2025). "While the cross-sectional design limits causal interpretation of the relationships between serum myostatin/irisin with sarcopenia/OP in Chinese RA patients." (PMID 40593203, 2025). "Elevated serum myostatin and reduced irisin levels are associated with sarcopenia and OPF in RA patients." (PMID 40593203, 2025). "Some studies revealed a significant relationship between myokine and phenotype of sarcopenia and/or physical frailty, such as myostatin and IL-15 associated with muscle weakness and/or wasting, IGF-1 with muscle weakness, slowness, disability." (PMID 38375321, 2024). "Dysbiosis in the gut promotes the induction of myostatin in skeletal muscle via LPS activation, and is a risk for the development of sarcopenia." (PMID 38256036, 2024).
sarcopenia (continued). "Hyperammonemia associated with decreased ammonia clearance due to cirrhosis also promotes the induction of myostatin in skeletal muscle, and is a risk factor for the development of sarcopenia." (PMID 38256036, 2024). "The biological process underlying sarcopenia is unclear, but the proteins myostatin and follistatin are involved in the balance between muscle breakdown and synthesis." (PMID 39585121, 2024). "Myostatin is a key protein associated with muscle inhibition, and its levels have been shown to be elevated in various sarcopenia disease models, including aged rats." (PMID 39451544, 2024). "This can reduce Myo D-dependent acetylation of histones near the promoters of MEF2C and myostatin genes, which in turn inhibits myostatin transcription and myogenic cell differentiation, thus causing sarcopenia." (PMID 37881635, 2023). "Increased myostatin has been associated with aging and is considered a possible mechanism for sarcopenia development." (PMID 38069340, 2023). "An animal study suggested that the loss of myostatin, a well-known negative regulator of skeletal muscle growth that causes sarcopenia, can lead to AF." (PMID 37881721, 2023). "For example, binding of HDAC11 to Myo D can reduce Myo D-dependent histone acetylation near the promoter of the myostatin gene, thus repressing its transcription and causing sarcopenia." (PMID 37881635, 2023). "Potential targets of NAFLD-associated sarcopenia include myostatin antibodies, growth hormone, testosterone, and ammonia-lowering agents." (PMID 38137592, 2023). "In conclusion, in our cohort of patients, lower levels of serum myostatin are not only associated with sarcopenia, but also with ACLF development and increased mortality." (PMID 37554924, 2023). "Myostatin inhibitors block the action of myostatin, thereby allowing for increased muscle growth and preventing muscle loss, especially in conditions such as sarcopenia." (PMID 37371730, 2023). "Second, sarcopenia is closely associated with MS and physical inactivity as insulin resistance in MS is associated with hyperinsulinemia and elevated myostatin levels, both of which reduce skeletal muscle mass." (PMID 38057912, 2023). "Sarcopenia in the elderly is primarily caused by anabolic resistance induced by myostatin, while secondary sarcopenia appears to be activated by catabolic processes." (PMID 38069224, 2023). "Specifically concerning the cancer-related sarcopenia, high levels of myostatin have been associated with pronounced muscle wasting in several cancerous animal models such as melanoma, colon, or Lewis lung cancer." (PMID 38136400, 2023). "There is a progressive decrease in myostatin levels as cirrhosis progresses, demonstrating an association of sarcopenia with the development of ACLF and increased mortality." (PMID 37554924, 2023). "The potential of myostatin inhibition in the treatment of sarcopenia associated with chronic kidney disease is under consideration." (PMID 37764858, 2023). "It is not only the correlation of myostatin with severity of sarcopenia that is important, but also its association with prognosis." (PMID 37554924, 2023). "Treatment of sarcopenia with bimagrumab, a human monoclonal antibody against type II activin receptors, causing them to act as myostatin inhibitors, increased skeletal muscle mass and strength and increased walking speeds." (PMID 35010726, 2022). "Presarcopenia and sarcopenia were independently associated with age and IS levels after adjusting for sex, diabetes mellitus, creatinine level, and myostatin/SMI." (PMID 36287929, 2022). "One study reports that obese people positively regulate myostatin levels and show an association between sarcopenia, obesity, and myostatin inhibitors, and report the low activity as the cause of increased myostatin." (PMID 35250869, 2022). "This study aimed to assess the association between serum myostatin and IS levels and sarcopenia in patients with CKD." (PMID 36287929, 2022).
sarcopenia (continued). "This is the first report of the association between serum myostatin and IS levels and sarcopenia in patients with CKD." (PMID 36287929, 2022). "Herein, we analyzed the association between serum myostatin and IS levels and sarcopenia in patients with CKD, by performing a post hoc analysis of baseline data extracted from the RECOVERY study (clinicaltrials.gov: NCT03788252) of 150 patients with CKD." (PMID 36287929, 2022). "Another study found higher serum myostatin as a significant risk factor of sarcopenia amongst male community-dwelling older adults." (PMID 36330524, 2022). "Serum MSTN has been reported to be a major risk factor of pre-sarcopenia and sarcopenia, whereas MSTN knockout (MSTN−/−) mice exhibited greater myofiber size, muscle weight, and grip strength than wild-type controls." (PMID 35457038, 2022). "Decreased irisin levels seem to be potentially associated to sarcopenia, whereas increased myostatin has shown to negatively impact on sarcopenia in pre-clinical studies." (PMID 34858322, 2021). "Muscle homeostasis is normally regulated by MSTN and its upregulation has been associated with SM degeneration and the muscle wasting of cachexia associated with cancer and sarcopenia." (PMID 34440852, 2021). "In contrast, increased serum myostatin and myostatin mRNA are associated with periods of inactivity, sarcopenia, and cachexia of chronic disease." (PMID 34368273, 2021). "The pathophysiology of sarcopenia is multifactorial, with the constant presence of intracellular oxidative stress associated with hormonal decline and increased myostatin signaling, which are closely associated with muscle dysfunction followed by atrophy." (PMID 34445222, 2021). "Irisin and myostatin, for instance, have been studied with regard to diagnostic accuracy in discriminating sarcopenic patients, and to possible connections between sarcopenia and liver disease." (PMID 34858322, 2021). "Increased levels of myostatin have been implicated in muscle wasting, and myostatin has been identified as a potential therapeutic target for sarcopenia." (PMID 34202133, 2021). "The key contribution to sarcopenia in patients with chronic liver diseases can be the hyperammonemia-induced upregulation of myostatin, which causes muscle atrophy via the expression of atrophy-related genes." (PMID 33803020, 2021). "Hyperammonemia increases the secretion of myostatin, a muscle growth inhibitor, and causes the development of sarcopenia." (PMID 33925660, 2021). "Chronic kidney disease is highly associated with sarcopenia because of catabolic state–related protein wasting, inflammation-related dysregulation of myostatin and activation of the ubiquitin–proteasome system (caspase-3)." (PMID 34299990, 2021). "With an intent to treat muscle wasting diseases like cachexia and sarcopenia, researchers extensively study the functional and structural involvement of myostatin (encoded by the MSTN gene)." (PMID 32298234, 2020). "First, we have shown the beneficial effects of MVC and RAPA on myostatin, a negative regulator of muscle mass that has been implicated in wasting conditions such as sarcopenia and cachexia." (PMID 32353830, 2020). "Previous studies have reported that serum myostatin levels are significantly elevated in patients with end-stage liver disease or sarcopenia, and are associated with poorer survival in cirrhotic patients compared with those who had low serum myostatin levels." (PMID 33198216, 2020). "Recent studies have demonstrated that myostatin, another protein induced by NF-κB, represses miR-486 expression and inhibitors of this molecule can overcome aging-associated sarcopenia." (PMID 31941005, 2020). "Sarcopenia has been associated with increased levels of myostatin, a negative regulator of muscle mass, and skeletal muscle inflammation." (PMID 33318308, 2020). "Increased ammonia levels have also been connected to an increase in myostatin expression in mammals, which has been shown to be linked with sarcopenia." (PMID 32629824, 2020).
sarcopenia (continued). "The chronic elevation of TGF-β1 and/or myostatin (also known as GDF-8) has been linked with the pathology of sarcopenia and other forms of muscle atrophy associated with disuse and cachexia, frequently observed in elderly patients." (PMID 31658594, 2019). "In this regard, it has been described that myostatin and activin, which are linked to sarcopenia, are also inhibitors of the myoblasts proliferation." (PMID 30271655, 2018). "Myostatin is associated with muscle catabolism and actually antibodies against myostatin were considered to prevent sarcopenia, cancer cachexia, and muscle wasting disorders." (PMID 28373915, 2017). "As a result, myostatin is a promising therapeutic target for conditions of compromised muscle health, including age-related sarcopenia, disease-associated cachexia, congenital myopathies, muscular dystrophies, disuse atrophy, and trauma." (PMID 26180626, 2015). "Myostatin modulation also has therapeutic potential for disease states that involve the loss of normal muscle mass, such as cancer cachexia, disuse atrophy, sarcopenia and microgravity exposure." (PMID 20161803, 2010). "Therefore, inhibiting myostatin-induced ROS production represents a promising strategy to minimize muscle loss characteristic of sarcopenia." (PMID 41228405, 2025). "However, further longitudinal studies and mechanistic research are warranted to validate these associations and to elucidate the roles of ApoJ and MSTN in muscle physiology and sarcopenia progression." (PMID 40661742, 2025). "Accumulating data show that myostatin increases with age, indicating that upregulation of myostatin protein secretion could result in sarcopenia by causing muscle wasting, along with increased fat mass." (PMID 39764565, 2025). "Notably, these findings highlight the potential of MSTN-ASO as a gene-targeted therapy for CKD-associated sarcopenia, a condition for which current treatment options remain limited." (PMID 40243849, 2025). "Myostatin has been implicated in several wasting conditions including sarcopenia and cachexia." (PMID 39797505, 2025). "Due to the central role of MSTN in controlling muscle growth, this myokine has been associated with the loss of muscle mass in sarcopenia, muscular dystrophy, and cachexia and is currently being investigated as a possible therapeutic target in these pathological conditions." (PMID 41303309, 2025). "With age, myostatin levels may increase, contributing to sarcopenia (the age-related loss of muscle mass and function)." (PMID 40427596, 2025). "Thus, Fractions 5–7 were confirmed as high‐purity EVs‐enriched fractions and subsequently used to quantify sarcopenia‐associated markers, including adiponectin, myostatin, P3NP, CRP and TNF‐α, within plasma‐derived EVs using ELISA." (PMID 40162588, 2025). "As a negative regulator of muscle growth, myostatin inhibition through MSTN mutations may delay sarcopenia by suppressing excessive protein degradation pathways." (PMID 40869996, 2025). "Elevated ApoJ and reduced MSTN levels are associated with sarcopenia in older adults." (PMID 40661742, 2025). "Additionally, Sharp scores and elevated myostatin levels serve as risk factors for sarcopenia, whereas irisin levels act as a protective factor against sarcopenia in RA patients." (PMID 40593203, 2025). "Additionally, Sharp scores and elevated myostatin levels serve as risk factors for sarcopenia, while irisin levels act as a protective factor against sarcopenia." (PMID 40593203, 2025). "This underscores the role of myostatin as a risk factor for sarcopenia." (PMID 40593203, 2025). "For example, myostatin antibodies may increase muscle mass, decrease body fat and improve physical function in older people with sarcopenia, a condition closely linked to frailty." (PMID 40863223, 2025). "However, studies show that myostatin levels increase with age and are associated with reduced muscle mass and functional performance—hallmark features of sarcopenia." (PMID 40944148, 2025).